TNFRSF12A (TNF receptor superfamily member 12A)
Description:
Receptor for TNFSF12/TWEAK. Weak inducer of apoptosis in some cell types. Promotes angiogenesis and the proliferation of endothelial cells. May modulate cellular adhesion to matrix proteins.
Synonyms: TweakR; CD266; FN14
Tractability: Antibody: a drug acting on it is in phase 2 or 3 trials; its Gene Ontology location is reachable by antibodies, with high confidence; UniProt predicts a signal peptide or a membrane-spanning region; the Human Protein Atlas places it where antibodies can reach.
Target class: Membrane receptor
Gene: Protein-coding gene on chromosome 16 (3,018,445 to 3,022,385, forward strand). Ensembl gene ENSG00000006327.
Subcellular location: Membrane
Subcellular location (Human Protein Atlas): Cytosol; Plasma membrane
Pathways (Reactome):
Immune System: TNF receptor superfamily (TNFSF) members mediating non-canonical NF-kB pathway; TNFR2 non-canonical NF-kB pathway
Gene Ontology:
Molecular function: protein binding
Biological process: positive regulation of apoptotic process; positive regulation of extrinsic apoptotic signaling pathway; regulation of wound healing; regulation of angiogenesis
Cellular component: plasma membrane; cell surface; membrane; ruffle
Genetic constraint (gnomAD): Loss-of-function variants: 13 observed, 13.73 expected, observed/expected ratio (o/e) 0.95, 90% interval 0.62 to 1.5. The synonymous counts are far from expectation, so gnomAD's model fits this gene poorly and the ratio says little. Missense variants: 174 observed, 144.35 expected, observed/expected ratio (o/e) 1.21, 90% interval 1.07 to 1.37. Synonymous variants: 89 observed, 62.12 expected, observed/expected ratio (o/e) 1.43, 90% interval 1.21 to 1.71.
Homologues: Orthologues: chimpanzee TNFRSF12A (100% identical), macaque TNFRSF12A (99% identical), guinea pig TNFRSF12A (88% identical), dog TNFRSF12A (86% identical), mouse Tnfrsf12a (81% identical), pig TNFRSF12A (61% identical), rabbit TNFRSF12A (57% identical).
Diseases named in the same sentence as TNFRSF12A in open-access papers:
TNFRSF12A is named in the same sentence as 224 diseases in open-access papers, as found by Europe PMC text mining. Sharing a sentence is not in itself a finding about the gene and the disease. The quoted sentences say what the papers report.
glioma (35 papers, 2007 to 2026). A benign or malignant brain and spinal cord tumor that arises from glial cells (astrocytes, oligodendrocytes, ependymal cells). "Knockdown of TNFRSF12A in glioma cells altered the expression of genes associated with amyloid precursor protein (APP) processing and Wnt signaling pathways." (PMID 40595248, 2025). "Univariate and multivariate regression analyses further confirmed the Riskscore, TNFRSF11b, and TNFRSF12a as independent risk factors in The Cancer Genome Atlas and Chinese Glioma Genome Atlas datasets." (PMID 35592520, 2022). "In our analysis, TNFRSF12A was more highly expressed in IDH wild-type gliomas than gliomas with IDH mutations." (PMID 33937046, 2021). "According to survival analysis, TNFRSF12A expression was associated with a shortened survival in glioma patients." (PMID 33937046, 2021). "Satisfactory results from survival, ROC curve, independent prognosis, and clinical correlation analyses in the CGGA and GSE43378 samples verified that TNFRSF12A was significantly associated with the prognosis of glioma patients." (PMID 33937046, 2021). "In conclusion, TNFRSF12A can serve as an independent risk factor to predict prognosis and has tremendous value in glioma immunotherapy." (PMID 33937046, 2021). "Overall, TNFRSF12A is significantly overexpressed in gliomas and closely associated with inflammatory processes." (PMID 33937046, 2021). "The survival time for the glioma patients in the high expression group was significantly shorter, suggesting that TNFRSF12A hyperexpression might be a risk factor for a poor prognosis of glioma patients." (PMID 33937046, 2021). "Therefore, our results supported the conclusion that TNFRSF12A expression could serve as an independent high-risk predictor for glioma patients." (PMID 33937046, 2021). "TNFRSF12A expression is usually low in normal tissues but significantly increases after tissue injury and in many solid tumor types, including glioma, breast cancer, esophageal adenocarcinoma, pancreatic cancer, and hepatocellular carcinoma." (PMID 39445005, 2024). "Studies suggest that TNFRSF12A exhibits reduced expression levels in healthy brain tissues, yet demonstrates increased expression in gliomas." (PMID 38560169, 2024). "Sequencing analysis has confirmed that TNFRSF12A mRNA levels are low in normal brain and increase with glioma grade." (PMID 35646656, 2022). "In summary, multiple research results have proven that TNFRSF12A is a potential glioma therapeutic target." (PMID 33937046, 2021). "A previous study demonstrated that nanoparticles targeting TNFRSF12A more accurately localized to gliomas compared to untargeted TNFRSF12A nanoparticles." (PMID 33937046, 2021). "Glioma samples from GSE43378 samples were grouped based on the median expression level of TNFRSF12A for differential analysis, and 645 DEGs were identified." (PMID 33937046, 2021). "Other studies have also confirmed that TNFRSF12A is overexpressed in melanomas, gliomas, and esophageal and pancreatic cancers." (PMID 34917619, 2021). "Using a comprehensive analysis based on multiple databases, we focused on TNFRSF12A, which is significantly overexpressed in gliomas." (PMID 33937046, 2021). "The immunohistochemical staining results validated the previous dataset analyses indicating that TNFRSF12A expression was progressively up-regulated in normal tissues, low-grade gliomas, and high-grade gliomas." (PMID 33937046, 2021). "Studies have revealed that specific drug modifications can improve the precision therapy of TNFRSF12A for gliomas." (PMID 33937046, 2021). "It has been reported that the expression of TNFRSF12A was significantly higher in recurring gliomas than in newly diagnosed primary tumors." (PMID 33937046, 2021). "Independent prognostic analysis of both groups illustrated that the expression level of TNFRSF12A was an independent prognostic factor for glioma." (PMID 33937046, 2021).
glioma (continued). "The results of the TIMER analysis validated the significant correlation of TNFRSF12A with immune cell infiltration and glioma survival." (PMID 33937046, 2021). "The differences in TNFRSF12A expression in normal brain, low-grade glioma, and high-grade glioma tissues were detected using immunohistochemical staining." (PMID 33937046, 2021). "TNFRSF12A is expressed at low levels in TMZ-sensitive gliomas and highly expressed in TMZ-resistant gliomas." (PMID 33937046, 2021). "Clinical correlation analysis of the CGGA data demonstrated that the expression level for TNFRSF12A was significantly correlated with PRS type, histology, grade, age, chemotherapy, IDH mutations, and 1p19q co-deletion in glioma samples." (PMID 33937046, 2021). "It has been well-established that excessive activation of the TWEAK/TNFRSF12A signaling pathway promotes glioma growth." (PMID 33937046, 2021). "The overexpression of TNFRSF12A in glioma cell lines significantly increased cell migration and invasion, which demonstrated the tumor-promoting effects of TNFRSF12A." (PMID 33937046, 2021). "The AUC values for both groups were high, which validated the accuracy of TNFRSF12A as a prognostic gene in predicting survival time in glioma patients." (PMID 33937046, 2021). "We concluded that TNFRSF12A was a viable prognostic biomarker and a potential immunotherapeutic target for glioma." (PMID 33937046, 2021). "The immunohistochemical staining results verified the progressive up-regulation of TNFRSF12A expression in normal brain, low-grade glioma, and high-grade glioma tissues." (PMID 33937046, 2021). "One study reported that TNFRSF12A promoted the invasive phenotype of IDH1 wild-type gliomas, while IDH1-mutant gliomas exhibited low TNFRSF12A mRNA and protein levels compared with IDH1 wild-type gliomas." (PMID 33937046, 2021). "Our analysis provides a more comprehensive demonstration of the roles of TNFRSF12A in glioma progression." (PMID 33937046, 2021). "The results revealed that TNFRSF12A was primarily expressed in the cytoplasm of cells, and TNFRSF12A expression was significantly higher in gliomas compared with normal brain tissue." (PMID 33937046, 2021). "Notably, TNFRSF12A is significantly overexpressed in gliomas, enhancing cell migration and invasion, thus reinforcing its tumor-promoting effects." (PMID 40595248, 2025). "In addition, the expression of TNFRSF12A was significantly higher in high-grade gliomas than low-grade gliomas." (PMID 33937046, 2021). "In our study, we found that the TNFRSF12A expression levels increased with the grade of the glioma." (PMID 33937046, 2021). "The expression of TNFRSF12A was up-regulated as the glioma grade increased." (PMID 33937046, 2021). "A nomogram was constructed using glioma prognostic correlates, including TNFRSF12A expression, primary-recurrent-secondary (PRS) type, grade, age, chemotherapy, IDH mutation, and 1p19q co-deletion in CGGA samples with an AUC value of 0.860, which illustrated the accuracy of the prognosis prediction." (PMID 33937046, 2021). "Moreover, in TMZ-sensitive and TMZ-resistant glioma cell lines, lower and higher TNFRSF12A levels were expressed, respectively." (PMID 33937046, 2021). "TNFRSF12A expression was higher in patients >41 years of age compared to patients ≤41 years of age and higher in recurrent and secondary gliomas than in primary gliomas." (PMID 33937046, 2021). "TNFRSF12A was found to be significantly overexpressed in gliomas." (PMID 33937046, 2021). "Thus, the TWEAK/TNFRSF12A/NF-kb axis might participate in the drug resistance exhibited by some gliomas." (PMID 33937046, 2021). "Thus, we suggest that TNFRSF12A contributes to the progression of glioma." (PMID 33937046, 2021). "There have been few studies on the expression and function of TRAF1 in glioma, so the role of TRAF1 in glioma can only be inferred from its interaction function with TNFRSF12A and its cancer-promoting effect in other types of cancers." (PMID 37005685, 2023).
glioma (continued). "The survival data from glioma patients in the CGGA and GSE43378 datasets were significantly different between the high and low TNFRSF12A expression groups (p < 0.001)." (PMID 33937046, 2021). "Glioma cells that are less sensitive to TMZ presented higher expression of TWEAK, TNFRSF12A, and NF-kb." (PMID 33937046, 2021). "High expression of TNFRSF12A has been reported in GBM and is also involved in glioma cell migration, invasion, and resistance to chemotherapeutic agents." (PMID 33803224, 2021). "TNFRSF12A, alternatively named FN14, belongs to the TNF/TNFR superfamily and has been reported to be involved in the initiation and progression of multiple tumor types, including glioma, pancreatic, breast, non-small-cell lung cancer, and colorectal cancer." (PMID 38660262, 2024). "TNFRSF12A exhibited higher expression in wildtype and 1p19q non-coding glioma compared to IDH mutants or 1p19q co-deletions." (PMID 33937046, 2021). "Through inhibition of Rac1 activation, ATA inhibited the TWEAK-induced glioma cell invasion process but did not affect cell viability or TNFRSF12A expression." (PMID 33937046, 2021). "Three immune genes related to glioma prognosis were identified as TGFB2, VIM, and TNFRSF12A." (PMID 33937046, 2021). "Expression of TNFRSF12A was significantly correlated with histology and grade in glioma patients and independent of age and gender, as seen in the GSE43378 samples." (PMID 33937046, 2021). "In this study, some important glioma-related genes were not differentially expressed in PDGFRA-overexpressing canine gliomas, including HIF1-α, CTLA4, DLL3, and TNFRSF12A, important mediators of angiogenesis, immune evasion, self-renewal, and invasion in the tumor microenvironment." (PMID 29352201, 2018).
breast carcinoma (21 papers, 2013 to 2025). "The newly discovered gene, TNFRSF12A, could be an important factor in explaining breast cancer progression associated with MMP-9." (PMID 30142200, 2018). "High levels of TNFRSF12A associated with MMP-9 overexpression may be important to explain the progression of breast cancer, and survival could be improved using therapy targeting TNFRSF12A." (PMID 30142200, 2018). "Studies have demonstrated that TNFRSF12A is highly expressed in breast cancer, and a high TNFRSF12A level associated with matrix metalloproteinase (MMP)-9 overexpression is related to cancer progression; thus, TNFRSF12A-targeting therapy could improve survival rates in cancer." (PMID 34917619, 2021). "Rb-loss reduces several ‘hallmarks’ of immune response in mouse models, and its deficiency correlates with the induction of PVR, CD274 and several other IC modulators, including ICOSLG and TNFRSF12A in human breast cancer." (PMID 37230983, 2023). "The TNF receptor superfamily member 12A (TNFRSF12A) gene is well known in cancer, for example, it is linked to poor prognosis in breast cancer." (PMID 30940089, 2019). "We found that high ERα expression is a protective factor for breast cancer survival, while high TNFRSF12A expression is a deleterious factor." (PMID 30301189, 2018). "Interestingly, the other upregulated genes are associated with features of cell proliferation (TNFRSF12A in human hepatocellular carcinoma), tumor progression (ISG20 in clear cell renal cell carcinoma), and cell survival (LGALS3 in breast cancer)." (PMID 37685859, 2023). "We identified TNFRSF12A as an MMP-9-related gene in patients with breast cancer." (PMID 30142200, 2018). "In another study that used TNFRSF12A as the target, researchers synthesized an immunoconjugate using recombinant gelonin toxin and ITEM4, which produced significant tumor-inhibiting results in a breast cancer xenograft model." (PMID 33937046, 2021).
glioblastoma (19 papers, 2007 to 2026). The most malignant astrocytic tumor (WHO grade IV). "It was found that compared to normal samples, TNFRSF12A was high-expressed in most tumors, such as STAD, colon adenocarcinoma (COAD), lung adenocarcinoma (LUAD), liver hepatocellular carcinoma (LIHC), and glioblastoma (GBM)." (PMID 40391219, 2025).
lupus (16 papers, 2013 to 2024). "TWEAK, the ligand of TNFRSF12A, has previously been reported to be involved in lupus pathology, and LIGHT (TNFSF14), a ligand of HVEM (TNFRSF14), is commonly dysregulated in murine lupus." (PMID 39688922, 2024). "Persistent TWEAK-Tnfrsf12a engagement or Tnfrsf12a overexpression contributes to acute ischemic stroke, rheumatoid arthritis, systemic lupus erythematosus, multiple sclerosis, and cancer." (PMID 35853848, 2022). "The lack of correlation of Akt2 with Tnfrsf12a in the lupus mouse model may be due to a discrepancy between Tnfrsf12a gene expression (quantified here) and its activation." (PMID 34440346, 2021). "Other TNF family receptors, including TNFRSF12A (TWEAKR) and TNFRSF14 (HVEM), showed heterogeneous expression patterns but were not significantly altered between lupus groups." (PMID 39688922, 2024).
hepatocellular carcinoma (15 papers, 2013 to 2025). A malignant tumor that arises from hepatocytes. "Based on the TCGA RNA-sequencing and methylation data, a previous study indicates that the methylation and expression levels of TNFRSF12A is significantly associated with prognosis of hepatocellular carcinoma, which can be used as a prognostic risk model." (PMID 33643183, 2021). "Expression of TNFRSF12A/FN14 increases after SARS-CoV infection of a human hepatoma cell line, Huh7." (PMID 34659373, 2021). "It was reported that TNFRSF12A knockout inhibits hepatocellular carcinoma cell proliferation and migration in vitro." (PMID 30857150, 2019). "Knockdown of TNFRSF12A can inhibit hepatocellular carcinoma cell proliferation and migration in vitro." (PMID 30301189, 2018). "Recent studies demonstrated that hepatic TNFRSF12A was markedly increased in NASH, alcoholic liver disease, chronic hepatitis C, and hepatocellular carcinoma." (PMID 36690641, 2023). "In conclusion, whether alcohol affects DNA methylase through one-carbon metabolism pathway and thus reduces the degree of methylation of TNFRSF12A through epigenetic effects, ultimately affecting the prognosis of patients with HCC hepatocellular carcinoma remains to be determined." (PMID 31998364, 2019).
melanoma (14 papers, 2013 to 2023). A malignant, usually aggressive tumor composed of atypical, neoplastic melanocytes. "Nevertheless, we were able to obtain reproducible up‐regulation of genes including EGR1, TXNIP, AXL, CYR61, LIMS2 and TNFRSF12A in MDA‐MB‐435s and MV3 melanoma cell lines and significant increase in protein levels as well, suggesting potential implication in other melanoma cells." (PMID 31044520, 2019).
rheumatoid arthritis (14 papers, 2006 to 2024). A chronic, systemic autoimmune disorder characterized by inflammation in the synovial membranes and articular surfaces. "Because TWEAK is a proinflammatory cytokine, prolonged TWEAK–Fn14 (TWEAKR/TNFRSF12A) axis signaling could theoretically play a role in diseases induced by excessive or aberrant inflammatory responses in humans, including rheumatoid arthritis and multiple sclerosis." (PMID 35742914, 2022).
autoimmune disease (13 papers, 2012 to 2022). A disorder resulting from loss of function or tissue destruction of an organ or multiple organs, arising from humoral or cellular immune responses of the individual to their own tissue constituents. "The expression of TNFRSF12A markedly increases in damaged tissue, autoimmune diseases, and inflammatory diseases such as SLE and autoimmune myocarditis." (PMID 33937046, 2021). "In addition, the other genes listed include PSMD14 and TNFRSF12A, which are related to key targets in the TNF pathway of autoimmune diseases." (PMID 33299893, 2020).
Cachexia (13 papers, 2016 to 2024). Severe weight loss, wasting of muscle, loss of appetite, and general debility related to a chronic disease. "Finally, expression of Tnfrsf12a and cachexia-induced weight loss can be inhibited in vivo by DM-aKG in a mouse cancer cachexia model." (PMID 37761958, 2023). "Our results show that under Gln-deprived conditions, global histone methylation of H3K4me3 increases, resulting in an upregulation of Tnfrsf12a and cachexia." (PMID 37761958, 2023). "Instead, our results suggest that Gln deprivation at the site of the tumor decreases the concentration of aKG, which stimulates Tnfrsf12a transcription as a form of metabolic adaptation that calls to distant sites for nutrients in the form of cachexia." (PMID 37761958, 2023). "Especially, TNFRSF12A (also known as TWEAK receptor, Fn14, or CD266) correlated with integrin β3 expression, which drives Glut3 expression, is associated with clinical outcome and tend to be responsible for inducing cachexia in tumors." (PMID 34238310, 2021). "Furthermore, a study has implicated tumor Fn14 (tumor necrosis factor receptor superfamily member 12A; TNFRSF12A) as an inducer of cachexia in mice models, and it was shown that the antibodies against Fn14 prevented tumor-induced cachexia and extended lifespan without chemotherapy." (PMID 34266478, 2021). "Although TNFRSF12A expression increased in human tumors, especially those with high cachexia incidence, a correlation between TNFRSF12A levels with weight loss in patients has not been established due to lacking information concerning the presence of cachexia in current patient databases." (PMID 37761958, 2023). "Pancreatic cancer PANC-1, a cachexia-inducing cell line, and CRC SW620 cells were deprived of either Gln, glucose, or serum for 24 h, and the expression of TNFRSF12A mRNA was measured via qPCR." (PMID 37761958, 2023).